TNF (tumor necrosis factor)
Diseases named in the same sentence as TNF in open-access papers (continued):
Sharing a sentence is not in itself a finding about the gene and the disease.
alopecia areata (21 papers, 2010 to 2025). Loss of scalp and body hair involving microscopically inflammatory patchy areas. "Less critical adverse effects are weight gain which is rarely reported in small observational studies in RA and spondyloarthropathy and hair loss (alopecia areata or generalized alopecia) which has been reported as case report mainly in psoriatic patients on anti-TNF therapy." (PMID 22927859, 2012). "Expanding on this, our study examined a broader range of cytokines, including IL-2, IL-4, IL-6, IL-10, IFN-γ, and TNF-α, to evaluate their potential correlation with the onset and progression of alopecia areata in blood assays." (PMID 40352276, 2025). "In analyzing cytokine and vitamin levels, we observed that individuals with alopecia areata exhibited elevated average levels of IL-4, IL-10, TNF-α, and IFN-γ, surpassing those of healthy controls." (PMID 40352276, 2025). "Studies have shown a positive relationship between alopecia areata severity and serum concentrations of several cytokines, including IL-2, TNF, IL-12, IL-17, and IL-17E." (PMID 41002719, 2025). "The alopecia areata group displayed slightly higher TNF-α levels, with an average of 0.775 ± 0.343 pg/mL and a median of 0.735 pg/mL, compared to the control group, where the average was 0.679 ± 0.325 pg/mL and the median 0.575 pg/mL." (PMID 40352276, 2025). "While the blood analysis revealed higher average levels of IL-4, IL-10, and TNF-α in alopecia areata patients compared to healthy individuals, these differences were not statistically significant." (PMID 40352276, 2025). "Alopecia areata is also connected with changes in levels of interleukin (IL)-6, tumor necrosis factor-α, IL-1β and Type 17 cytokines." (PMID 38892934, 2024). "Numerous studies demonstrated an increased serum level of TNF in patients with alopecia areata compared to healthy controls." (PMID 34943905, 2021). "However, numerous studies indicate that alopecia areata is associated with a systemic immune activation and the dysregulation of multiple proinflammatory cytokines, including Interleukin 1 beta (IL-1β), IL-6, tumor necrosis factor alpha (TNF-α), and interferon gamma (IFN-γ)." (PMID 34830700, 2021). "Positive correlations between the severity of alopecia areata and an increased serum level of various cytokines including IL-2, TNF, IL-12, IL-17, and IL-17E were reported in the literature." (PMID 34943905, 2021). "The dysregulation of the serum level of Th1, Th2 and Th17 cytokines including proinflammatory markers, such as IL-2 and TNF, indicates that alopecia areata is a systemic inflammatory disorder not limited to the hair follicles." (PMID 34943905, 2021). "According to the literature, a positive correlation was reported between the severity of alopecia areata and the serum level of various cytokines including IL-2, TNF, IL-12, IL-17, and IL-17E." (PMID 34943905, 2021). "Several cases have been published mentioning de novo development of alopecia areata due to TNF-α blockers." (PMID 31440261, 2019). "In addition, TNF-α blockade induces a Th17 immune response and down-regulation of Treg cells, which are dysfunctional in alopecia areata." (PMID 40481366, 2025). "Although the variations in cytokines and vitamins such as IL-2, IL-4, IL-6, IL-10, TNF-α, and vitamins in the blood are insufficient to differentiate alopecia areata, we have observed a notable increase in IFN-γ and decrease in IgG4 levels among patients with this condition." (PMID 40352276, 2025). "The mean serum levels of IL-6, TNF-α, IL-17A, and IL-21 were comparable between the two sexes, with p values exceeding 0.05, indicating that gender did not appear to influence the systemic inflammatory response in alopecia areata." (PMID 41002719, 2025). "In conclusion, both IL-15 and TNF-α are markers for alopecia areata." (PMID 37206670, 2023). "Plasmatic TNF-α (tumor necrosis factor α) is also increased in patients with alopecia areata." (PMID 36292745, 2022).
alopecia areata (continued). "Moreover, an increased expression of TNF mRNA was reported in peripheral blood mononuclear cells in patients with alopecia areata compared to healthy individuals." (PMID 34943905, 2021). "Differences in TNF-α serum level (pg/ml) in relation to clinical data in alopecia areata patients." (PMID 33370782, 2020). "Relation between TNF-α-308-G/A and clinical characteristics in alopecia areata patients." (PMID 33370782, 2020). "TNF-α is well known to play a major role in the pathogenesis of alopecia areata." (PMID 20300578, 2010). "A suggested explanation of this failure might be that TNF-α is just one of the ever expanding list of cytokines involved in the pathogenesis of alopecia areata." (PMID 20300578, 2010). "Alopecia areata is characterized by systemic dysregulation of Th1 (IL-2, IFN-γ, TNF and IL-12), Th2 (IL-6), and Th17 (IL-17, IL-21) cytokines." (PMID 34943905, 2021). "Other studies showed increased ACTH and α-MSH levels in alopecia areata patients, suggesting the presence of an active neurogenic system and local HPA axis activity, with positive correlations with TNF-α level." (PMID 20300578, 2010). "Based on our analysis, it may be suggested that alopecia areata is characterized by the dysregulation of systemic Th1 (IL-2, IFN-γ, TNF and IL-12), Th2 (IL-6), and Th17 (IL-17, IL-21) cytokines." (PMID 34943905, 2021). "TNF-α levels in the skin correlate positively with plasma ACTH levels and cutaneous ACTH receptor expression levels under repeated stress in humans, possibly suggesting a pathophysiologic mechanism lying behind the well-known role of stressors in alopecia areata." (PMID 20300578, 2010).
chronic bronchitis (21 papers, 2006 to 2025). A type of chronic obstructive pulmonary disease characterized by chronic inflammation in the bronchial tree that results in edema, mucus production, obstruction, and reduced airflow to and from the lung alveoli. "Previous work has shown that COPD/chronic bronchitis subjects with alpha-1 antitrypsin deficiency with the rs361525 TNF-α single nucleotide polymorphism have 100 times more TNF-in spontaneous sputum than disease matched controls." (PMID 26620975, 2015). "Several gene studies have also determined that the promoter polymorphism of TNF-α is associated with chronic bronchitis or the extent of emphysematous changes." (PMID 23267696, 2012). "Despite maximising our numbers in this way we were unable to show any TNFα effect on quantitative phenotypes, again emphasising the specificity of association with chronic bronchitis." (PMID 18620570, 2008). "The patients with chronic bronchitis and impaired lung function had a prevalence of the TNFα -308A allele as compared to the control subjects." (PMID 17034639, 2006). "Variation in TNFα is associated with chronic bronchitis in AATD." (PMID 18620570, 2008). "The main KEGG pathways were prominently involved in chronic bronchitis, including the TNF signaling pathway (hsa04668), and IL-17 signaling pathway (hsa04657)." (PMID 40788315, 2025). "Among these, the TNF and IL-17 signaling pathways were notably involved in regulating the inflammatory and immune responses of chronic bronchitis." (PMID 40788315, 2025). "Although there is a degree of overlap of COPD phenotypes, our results are specific to chronic bronchitis, and concur with prior evidence regarding a role for TNFα in airways disease." (PMID 18620570, 2008). "Anti-TNF therapy has been disappointing in COPD, but was not assessed specifically in chronic bronchitis despite the importance of TNFα in the pathophysiology of the condition." (PMID 18620570, 2008). "In this context, our results revealed that the effectiveness of the model to induce chronic bronchitis is mainly characterized by increased number of neutrophils and lymphocytes in BAL, followed by increased levels of proinflammatory cytokines (IL-1β, IL-6, CXCL1, IL-17, and TNF-α)." (PMID 29326759, 2017).
chronic rhinosinusitis (21 papers, 2009 to 2025). Chronic form of sinusitis. "We identified new associations with potential biological relevance including SNPs in tumor necrosis factor (TNF) and ankyrin-related genes associated with acute and chronic sinusitis and acute respiratory tract infection." (PMID 27508393, 2016). "Systemic inflammation, exemplified by gut dysbiosis, abdominal fat tissue, silicone breast implants, chronic sinusitis, and psychological stress, is associated with elevated levels of interleukin-6 (IL-6), tumor necrosis factor-alpha (TNF-α), and transforming growth factor-beta (TGF-β)." (PMID 40725146, 2025). "Moreover, studies on chronic sinusitis suggested the presence of specific clusters of patients showing an IL-5 driven phenotype with a peculiar expression of other cytokines (e.g., TNFα) underlining the need of better characterizing these patients from a molecular point of view." (PMID 34356836, 2021). "IL-1β and TNF-α play a major role in the progression of acute sinusitis and that IL-3 dominates the cytokine profile in chronic sinusitis—leading to the coordinating effects of a variety of inflammatory cells." (PMID 38248349, 2024). "Macrophages play a role in TNF-α production and are also elevated locally and peripherally in chronic rhinosinusitis." (PMID 38474043, 2024). "It has been demonstrated that TNF-α is a pro-inflammatory cytokine involved in chronic rhinosinusitis." (PMID 38474043, 2024). "When compared to the normal human nasal mucosa, TNF was significantly higher in chronic rhinosinusitis with polyp patients." (PMID 35287308, 2022). "We found that ACE2 messenger RNA levels were positively correlated with pro-inflammatory cytokines (tumour necrosis factor-α (TNF-α) and IL-1β) and negatively correlated with eosinophil-related chemokines (eotaxin-3) in chronic rhinosinusitis patients." (PMID 33928889, 2021). "A continuous local production of TNFα within the olfactory mucosa in chronic rhinosinusitis patients results in a progressive inflammation with olfactory loss." (PMID 28025644, 2016). "Finally, Qing and colleagues measured elevated levels of miR-142-3p and TNF-α in chronic rhinosinusitis." (PMID 38612530, 2024). "In addition, in patients with chronic rhinosinusitis, miR-142-3p may participate in regulation of the body’s inflammatory response (TNF-α expression) through lipopolysaccharide stimulation in human nasal epithelial cells." (PMID 31980721, 2020). "In fact, transgenic mouse models of chronic rhinosinusitis, where TNF-α can be expressed in the olfactory epithelium in a temporally controlled manner, show disruption of the neuroepithelium when TNF-α expression was experimentally induced." (PMID 34445619, 2021). "In chronic rhinosinusitis patients, TNF-α and IL-1β messenger RNA levels were positively correlated with ACE2 (r = 0.4971 for TNF-α and r = 0.3082 for IL-1β)." (PMID 33928889, 2021). "In contrast, the non-eosinophilic chronic rhinosinusitis patients tended to show higher ACE2, TNF-α and interleukin (IL)-1β messenger RNA levels than controls, but the difference was not significant." (PMID 33928889, 2021).
Fulminant hepatitis (21 papers, 2009 to 2025). Acute hepatitis complicated by acute liver failure with hepatic encephalopathy occurring less than 8 weeks after the onset of jaundice. "Later, it was shown that d-galactosamine (d-GalN), a transcriptional inhibitor, sensitizes wild-type mice to lethal toxicity of LPS and TNF and that administration of either LPS or TNF to d-GalN-sensitized mice caused fulminant hepatitis." (PMID 35122118, 2022). "The general mechanism underlying hepatocyte apoptosis in fulminant hepatitis is the activation of extrinsic death-receptor-mediated apoptotic pathway by TNFα and Fas ligand." (PMID 29348606, 2018). "To examine the anti-TNF-α effect of MA-35 in vivo, we next examined the effect in the LPS/D-galactosamine (D-GalN) induced-fulminant hepatitis mice model, in which TNF-α plays a main pathway in the pathogenic condition." (PMID 28507324, 2017). "There is strong evidence that D-GalN/LPS-induced acute liver injury and fulminant hepatitis are associated with liver infiltration with inflammatory immune cells with subsequent abundant increase in the production of proinflammatory mediators including TNF-α and COX-2." (PMID 24799907, 2014). "Treatment of mice with LPS/D-GalN induces fulminant hepatitis, which is mediated by TNF-α and characterized by massive hepatic apoptosis." (PMID 33746949, 2021). "Our investigations demonstrated that RIPK1 protects hepatocytes from TNF-α secreted from macrophages during viral induced fulminant hepatitis." (PMID 30622241, 2019). "Intrigued by an earlier report describing the generation and phenotype of Bad−/− mice that reported normal cell death responses upon TNF treatment, we decided to reinvestigate the role of Bad in TNF-driven cell death ex vivo and in fulminant hepatitis." (PMID 25611386, 2015). "In fact, during the treatment with anti-TNF agents, several cases of transient viral reactivation, regressed with antiviral therapy, and rare cases of fulminant hepatitis have been reported, particularly in patients treated with infliximab." (PMID 23606869, 2013). "The hepatocytes death of this kind of mice fulminant hepatitis model is mainly mediated by TNF-a which subsequently leads to hepatic necrosis." (PMID 24282426, 2013). "The plasma concentrations of the final two elevated cytokines (TIMP-1 and TNF-α) are significantly increased in patients with fulminant hepatitis, reflecting severe hepatic inflammation." (PMID 19317920, 2009). "Additionally, it was also found to diminish cell apoptosis in liver tissues of fulminant hepatitis and prevented Act D/TNFα-stimulated cell death both in primary hepatocytes and HepG2 cell lines." (PMID 29348606, 2018). "In mice with fulminant hepatitis, TEC can protect the liver against inflammatory damage by downregulating TLR4, IL‐6, TNF‐α, iNOS, and COX‐2 expressions." (PMID 38722267, 2024). "FGL2 together with C5aR and TNF-α contribute to coagulation and complement activation during MHV-3-induced fulminant hepatitis." (PMID 30419833, 2018). "Notably, despite high ALT levels, TNF-treated animals never developed fulminant hepatitis or succumbed to death." (PMID 30442932, 2018).
hemophagocytic lymphohistiocytosis (21 papers, 2004 to 2026). "Patients with CGD have excessively high levels of cytokines, such as TNF-α, IL-1, IL-8, which predispose them to hemophagocytic lymphohistiocytosis (HLH) when infected." (PMID 35365205, 2022). "In T-cell lymphoma, the hemophagocytic syndrome is assumed to be caused by cytokines, especially, tumor necrosis factor-α, and interferon-γ released from neoplastic T-cells." (PMID 15491503, 2004). "Among 20 patients with secondary Hemophagocytic lymphohistiocytosis (sHLH), levels of IL-10 and TNF-α were significantly elevated compared to other MS cases without sHLH (P < 0.001 and P= 0.025, respectively)." (PMID 41176307, 2025). "Inhibition of both IFN gamma and TNF alpha was effective in reduction of inflammatory cell death in experimental models of sepsis, hemophagocytic lymphohistiocytosis (HLH), and cytokine shock." (PMID 34149697, 2021). "Excessive activation of monocytes attributable to stimulation by high levels of Th1 cytokines, such as interferon-γ, tumor necrosis factor-α, interleukin (IL)-1 or IL-6, are proposed as possible immunopathologic mechanism of hemophagocytic lymphohistiocytosis." (PMID 15496237, 2004). "The cytokine storm of IL-2, IL-6, TNF-α, and IFN-γ observed in both forms of hemophagocytic lymphohistiocytosis (HLH) induces a hyperactivated state of both macrophages and cytotoxic T cells." (PMID 39318634, 2024). "Hemophagocytic lymphohistiocytosis (HLH) is a rare, highly inflammatory disorder resembling cytokine storm involving proliferation of activated T cells and macrophages with the release of large amounts of cytokines, particularly IFN gamma, TNF, and GM-CSF." (PMID 35323191, 2022).
IgA nephropathy (21 papers, 2013 to 2025). "The supernatant suspensions that contain IgA1 from IgA nephropathy patients will promote the expression of TNF and its receptors by human mesangial cells and glomerular hyperpermeability and proteinuria will be caused." (PMID 39492771, 2025). "Tubular cells of IgA nephropathy patients also overexpressed genes of the inflammatory TNF signaling pathway." (PMID 35328704, 2022). "Tubular cells of IgA nephropathy patients were enriched in inflammatory pathways, including TNF-α signaling." (PMID 35328704, 2022). "Because the serum level of TNF-α is reported to be correlated with the severity of IgA nephropathy, it is possible that CL-1 expression is also induced by TNF-α in humans." (PMID 35271660, 2022). "Serum TNF-α was measured by chemiluminescence immunoassay in 53 renal biopsy-proved IgAV-N patients, 53 healthy controls, and 53 IgA nephropathy (IgAN) patients." (PMID 33299497, 2020). "In our case, the activity of IgA nephropathy was exacerbated by anti-TNFα therapy but was improved by the combination of corticosteroids, tonsillectomy, and an IL-17A inhibitor against the original disease." (PMID 32842976, 2020). "Tumor necrosis factor alpha (TNF-α) is considered to play an important role in the pathogenesis in IgA nephropathy (IgAN)." (PMID 30428849, 2018). "Previous studies have shown that Perilla frutescens leaf extracts possess different biological activities, including inhibition of tumor necrosis factor-α (TNF-α), suppression of IgA nephropathy, and anti-inflammatory and anti-allergic activity." (PMID 24204835, 2013). "It is therefore conceivable to hypothesize a role of TNF-α in the pathogenesis and progression of IgA nephropathy." (PMID 37510392, 2023). "TNF-α and IL-6 are both common proinflammatory factors in IgA nephropathy." (PMID 36865740, 2023). "The CP improved kidney inflammation and fibrosis in IgA nephropathy rat models by reducing MCP-1, TNF-α, IL-1β, and IL-6 levels." (PMID 33806085, 2021). "For example, in IgA nephropathy, glomerular fibrosis results from IgA activation of mesangial cells to secrete TNF-α, IL-6 and TGF-β and in patients with IgA nephropathy, significantly reduced levels of glomerular BMP-7 were demonstrated in renal biopsy samples." (PMID 37626268, 2023).